IGF2BP1 (insulin like growth factor 2 mRNA binding protein 1)
Diseases named in the same sentence as IGF2BP1 in open-access papers (continued):
Sharing a sentence is not in itself a finding about the gene and the disease.
cancer (continued). "The conserved pro-oncogenic potential of oncofetal RBPs (oncoRBPs), such as MSI1 or IGF2BP1, suggests these as candidate targets in cancer treatment." (PMID 33291443, 2020). "These were among 31 transcripts (black and red) showing association with IGF2BP1 in primary tumors (R > 0.15) and consistent downregulation (log2FC < –0.5) upon IGF2BP1 depletion in cancer cells (dashed lines)." (PMID 32761127, 2020). "IGF2BP1 is overexpressed in human HCC, which is associated with cancer progression and poor prognosis." (PMID 32917856, 2020). "Poor survival rates in patients were associated with the increased expression of these genes across cancer types, such as IGF2BP1 (HR = 1.324527, P = 2.38E-06) in LUAD and IGF2BP2 (HR = 1.198617, P = 0.006603) and IGF2BP3 (HR = 1.570331, P = 0.000198) in LIHC." (PMID 33519919, 2020). "The expressions of IGF2BP1/2/3 were regulated by genome alterations, particularly copy number amplification in cancer." (PMID 33575259, 2020). "IGF2BP1’s main and conserved role in cancer-derived cells relies on the 3′UTR- and miRNA-dependent regulation of mRNA turnover." (PMID 32761127, 2020). "In agreement with decreased mRNA abundance, E2F1 protein expression was substantially reduced in all tested cancer cell lines upon IGF2BP1 depletion." (PMID 32761127, 2020). "Among cancers with substantially upregulated IGF2BP1 expression were four with reported pro-oncogenic roles of IGF2BP1 (LIHC, LUAD, OV and SKCM) as well as PAAD." (PMID 32761127, 2020). "IGF2BP1 depletion resulted in conserved downregulation of reporter activity in all analyzed cancer cell lines." (PMID 32761127, 2020). "Our study strongly suggests that METTL3/14-directed m6A-modification is a conserved mechanism promoting elevated cell cycle progression in IGF2BP1-expressing cancers." (PMID 32761127, 2020). "Studies reported that IGF2BP1 has been traditionally regarded as an oncogene and potential therapeutic target for cancers." (PMID 32426332, 2020). "H19 is a 2.3-kb-long, spliced and polyadenylated lncRNA that is, similarly to IGF2BP1, expressed during embryonic development and reactivated in several types of cancer." (PMID 32340118, 2020). "Using the Gene Set Enrichment Analysis (GSEA), we found that IGF2BP1, VIRMA, and ZC3H13 are all associated with pathways in cancer and WNT signaling pathway." (PMID 32950970, 2020). "The main role of IGF2BP1 in cancer cells is the impairment of miRNA/RISC-directed mRNA decay by safe-guarding target mRNAs in cytoplasmic mRNPs." (PMID 32761127, 2020). "In these five cancers, IGF2BP1 followed by LIN28B were the in average most upregulated mRNA-binding proteins (mRBPs) among 660 detected and reported by the RBP census." (PMID 32761127, 2020). "Our studies suggested that IGF2BP1 is a conserved post-transcriptional enhancer of E2F-driven transcription in cancer." (PMID 32761127, 2020). "In agreement, the activity of E2F-promoter luciferase reporters was consistently decreased by IGF2BP1 depletion in all here investigated cancer cell lines." (PMID 32761127, 2020). "Impaired G1/S-progression upon IGF2BP1 depletion was also observed in four cell lines derived from the four other cancers investigated here." (PMID 32761127, 2020). "Predominantly expressed in the embryo, IGF2BP1 is an essential mediator through the interaction with RNAs in various cancers." (PMID 32272940, 2020). "Given the importance of IGF2BP1 in cancer development, for example by regulating c-Myc and HULC, future studies will most likely put a stronger focus on how this RBP is regulated." (PMID 32340118, 2020). "It has been reported that THOR, a lncRNA with a cancer/testis expression pattern that exhibits a conserved interaction with IGF2BP1, potentially promoted oncogenesis." (PMID 32552789, 2020). "BTYNB interfered with cancer cell proliferation and expression of some prior known IGF2BP1 target transcripts." (PMID 32761127, 2020).
cancer (continued). "In all analyzed cancer cells, IGF2BP1 depletion significantly reduced E2F1–3 mRNA levels, with the exception of A549 cells where E2F3 transcripts were modestly elevated." (PMID 32761127, 2020). "In the vast majority of cancers, IGF2BP1 synthesis was substantially upregulated, supporting its oncofetal expression and conserved prognostic relevance." (PMID 32761127, 2020). "IGF2BP1 also regulates the localizations of mRNAs related to cell motility and focal adhesions to impact cancer invasion and metastasis." (PMID 32967226, 2020). "The evaluation of IGF2BP1-CLIP studies revealed enriched 3′UTR-association of E2F_TARGET transcripts among mRNAs downregulated by IGF2BP1 depletion in five cancer cell lines (dark to light blue)." (PMID 32761127, 2020). "In conclusion, these findings suggest SRF/IGF2BP1-dependent gene expression as a novel therapeutic hub in cancer treatment." (PMID 30371874, 2019). "The m6A-modification of the MYC mRNA promotes the association of IGF2BP1 resulting in reduced decay of the MYC transcript and consequently enhanced the expression of this oncogene in cancer cells." (PMID 30371874, 2019). "In cancer cells, we demonstrate that IGF2BP1 promotes the expression of SRF in a conserved and N6-methyladenosine (m6A)-dependent manner by impairing the miRNA-directed decay of the SRF mRNA." (PMID 30371874, 2019). "This suggested that IGF2BP1 depletion interferes with SRF/TCF- as well as SRF/MRTF-dependent transcriptional regulation in cancer cells mainly by reducing cellular SRF abundance." (PMID 30371874, 2019). "This confirms IGF2BP1 as a conserved ‘oncogenic’ m6A-reader in cancer and supports the view that IGF2BP1 impairs the miRNA-directed decay of target mRNAs by sequestering transcripts in miRNA-/RISC-free mRNPs." (PMID 30371874, 2019). "Although CLIP-hits in the 3′UTR of the SRF mRNA were reported for all three IGF2BPs, only the depletion of IGF2BP1 interfered with the expression of SRF in cancer cells." (PMID 30371874, 2019). "This was analyzed by monitoring the activity of SRF/TCF- and SRF/MRTF-dependent luciferase reports in cancer cells upon the depletion of IGF2BP1 or SRF." (PMID 30371874, 2019). "Together this suggests that the ‘oncogenic potential’ of IGF2BP1 is enhanced in cancers with upregulated m6A-modification in IGF2BP1-target mRNAs." (PMID 30371874, 2019). "In this study, we identify the SRF-encoding (serum response factor) mRNA as a conserved target mRNA of IGF2BP1 in cancer." (PMID 30371874, 2019). "In conclusion, these findings identify the SRF/IGF2BP1-, miRNome- and m6A-dependent control of gene expression as a conserved oncogenic driver network in cancer." (PMID 30371874, 2019). "Here, we demonstrate that the mRNA-binding protein IGF2BP1 is a conserved post-transcriptional enhancer of SRF-driven transcription in cancer." (PMID 30371874, 2019). "This regulation was associated with a substantial recovery of spheroid growth upon SRF depletion suggesting that FOXK1 and PDLIM7 are part of a SRF/IGF2BP1-dependent ‘effector network’ in cancer cells." (PMID 30371874, 2019). "The activity of both reporters was substantially diminished by the depletion of either IGF2BP1 or SRF in all cancer cells analyzed." (PMID 30371874, 2019). "The majority of these SRF/IGF2BP1-enhanced genes, including PDLIM7 and FOXK1, show conserved upregulation with SRF and IGF2BP1 synthesis in cancer." (PMID 30371874, 2019). "Both transcripts (FOXK1 and PDLIM7) were decreased upon the knockdown of IGF2BP1 suggesting a substantial conservation of SRF/IGF2BP1-dependent regulation of both factors in cancer cells." (PMID 30371874, 2019). "Two of these 35 mRNAs, PDLIM7 and FOXK1, showing a significant and positive association with both, IGF2BP1 and SRF expression in cancer, as indicated for HCC and EOC, were chosen for validating regulation by IGF2BP1 and SRF." (PMID 30371874, 2019).
cancer (continued). "Accumulating studies observed the abnormal expression of IGF2BP1 in various human cancer types, and indicated its oncogenic roles." (PMID 30220021, 2019). "In view of recent reports, these findings suggested that IGF2BP1 promotes SRF expression in cancer by impairing the miRNA-dependent decay of the SRF mRNA." (PMID 30371874, 2019). "The potential use of inhibitors of IGF2BP1 and its related pathways in cancer therapy was also discussed." (PMID 29954406, 2018). "The comprehensive description in the regulative mechanisms of IGF2BP1 in human cancers is little, although this gene has been demonstrated to play important roles in tumorigenesis and drug-resistance of cancer therapy in vitro and in vivo studies." (PMID 29954406, 2018). "Though currently available inhibitors of ncRNA-IGF2BP1-mRNA target-axes are limited, an inhibitor of IGF2BP1 binding to targeted mRNAs, BTYNB, has showed therapeutic potential by inhibiting cell proliferation of IGF2BP1-positive cancer cells." (PMID 29954406, 2018). "Functional validation of IGF2BP1 demonstrated its role in cancer cell proliferation/migration and offers a putative novel therapeutic target molecule for RB." (PMID 27799869, 2016). "Previous studies about IGF2BP1 in cancers mainly focus on its expression and/or correlations between its expression and clinical variables." (PMID 27588393, 2016). "Of the many RBPs that bind to the KRAS 3′ UTR, AGO2, HuR (or ELAVL1), IGF2BP1/2/3, PUM2, EWSR1, TAF15, FUS, and TIA1 have been previously implicated in cancer." (PMID 26930719, 2016). "Invasive carcinoma cells derived from primary mammary tumors have reduced levels of an RNA binding protein IMP1/ZBP1/IGF2BP1, required for β-actin mRNA localization." (PMID 27655671, 2016). "In cancer-derived cells, IGF2BP1 is essential for stabilizing target mRNAs during cellular stress, as shown here and previously." (PMID 25488811, 2015). "Genes that have been previously associated with MD and various other cancers showed differential marks that are either MD-induced (MX1, CTLA-4, EAF2 and GAL) or line-specific (IGF2BP1 and MMP2)." (PMID 23072359, 2012). "Consistent with its role in early developmental stages, the IGF2BP1 gene is downregulated in differentiated cell types, and overexpression of IGF2BP1 is known to occur in multiple human cancers, including breast, lung and colon." (PMID 21812971, 2011). "From our identified loci, IGF2BP1 and RAD51L1 have been implicated in cancer as have HOXB2, 2q35, and HMGA2." (PMID 20195514, 2010). "Interestingly, increased IGF2BP1 expression has been confirmed in non-small cell lung cancer tissues and cancer stem cells." (PMID 40986143, 2025). "Interestingly, another report confirmed that IGF2BP1 can bind to Kras RNA and that an inhibitor of IGF2BP1 induces lower Kras protein levels in cancer cells." (PMID 41394407, 2025). "Studies using mouse models in which IGF2BP1 was knocked out or knocked down suggest that molecules inhibiting IGF2BP1 could have therapeutic potential in cancer treatment." (PMID 40629079, 2025). "Moreover, compound 7773 demonstrated significant inhibitory effects on OC and lung adenocarcinoma cells, suggesting its potential for targeting IGF2BP1-related pathways in various cancers." (PMID 40823087, 2025). "circHIPK3 contains multiple sites for the same RBPs (e.g., DDX54, EIF4A3, FMR1, IGF2BP1, IGF2BP2, LIN28B and MOV10), many of which are involved in chemoresistance and organelle-like structures, such as Cajal body and P-body which are associated with cancer." (PMID 40061896, 2025). "In addition, IGF2BP1 is upregulated in most cancers and retains strong oncogenic potential, highlighting its promise as an immunotherapy target." (PMID 41437377, 2025). "Apparently, IGF2BP1 has the potential to serve as a target for cancer treatment." (PMID 41394407, 2025). "Next, we will further summarize the specific roles of IGF2BP1 in different hallmarks of cancer." (PMID 40584294, 2025).
cancer (continued). "IGF2BP1 could promote the expression of cancer-related genes by recognizing their m6A sites, thereby altering cell characteristics, and eventually, malignancy." (PMID 40584294, 2025). "Taken together, IGF2BP1 plays a significant role in regulating metabolic reprogrammings in cancer cells as it could control glucose metabolism, lipid metabolism, and glutathione metabolism mediating m6A modification." (PMID 40584294, 2025). "In NCI-H929 IGF2BP1-KD cells, pathways in cancer progression were found to be the most significantly enriched in relation to IGF2BP1 down-regulation (P < 0.001, Q < 0.001), suggesting that IGF2BP1 might play a significant role in MM development." (PMID 39534570, 2024). "Notably, IGF2BP1 (insulin-like growth factor 2 mRNA binding protein 1), MIR192 (microRNA mir-192), and CACD5 (cell division cycle associated 5) are significantly enriched in the KEGG pathway of MicroRNAs in cancer." (PMID 39273692, 2024). "IGF2BP1 is rarely observed in adult life but is upregulated or regenerated in cancer." (PMID 38166832, 2024). "For inhibitors of the m6A-recognition protein, a compound called “7,773” has been found to bind IGF2BP1 and inhibit its interaction with KRAS RNA, thereby reducing the expression of KRAS protein and downstream signaling, inhibiting the cancer-promoting activity of IGF2BP1." (PMID 38343637, 2024). "As a result, IGF2BP1 has been widely regarded as an oncogene and a cancer therapy target." (PMID 39679845, 2024). "Collectively, m6A-associated MLOs, including nYACs, RBM15 condensates, IGF2BP1 condensates, SGs and YBX2-YTHDF2 condensates, ensure stable oncogenic mRNA metabolism by regulating RNA decay, nuclear export, stability and translation in cancer cells." (PMID 39239525, 2024). "Furthermore, an upregulation of IGF2BP1 in leukemia, as frequently observed in other cancer types, cannot be seen in the TCGA acute myeloid leukemia cohort RNA-seq data." (PMID 37515119, 2023). "In colorectal cancer, IGF2BP1 and IGF2BP3 might act as potential biomarkers for screening high-risk groups and cancer patients." (PMID 37280679, 2023). "Consequently, IGF2BPs possess significant cancer-promoting properties, with IGF2BP1 and IGF2BP3 abnormally re-expressed in malignancies considered bona fide oncofetal proteins." (PMID 37280679, 2023). "Mechanistically, akin to IGF2BP1, IGF2BP3 protects let-7 target transcripts, including HMGA2 and LIN28B, by disrupting RISC association and upregulating expression in development and cancer." (PMID 36307883, 2022). "In addition, they also found that miR-506 can directly target the IGF2BP1 gene and can play a role in cancer suppression by regulating the expression level of IGF2BP1." (PMID 35688823, 2022). "Thus, IGF2BP1, as an m6A-reader, plays as an important oncogene in cancer by stabilizing or enhancing mRNA of its oncogenic factors, and thus IFG2BP1 is druggable for cancer treatment." (PMID 35541906, 2022). "Moreover, LIN28A/LIN28B and IGF2BP1/2/3 were the most differentially upregulated RBPs in over 5 cancer types." (PMID 35654793, 2022). "In addition, BTYNB has been shown to affect IGF2BP1-dependent mRNA stabilization leading to reduced cancer progression in vitro and in vivo." (PMID 35565249, 2022). "However, IGF2BP1-3 can be re-expressed in a broad range of cancer types and diverse cancer cell lines, where their expression often correlates with poor prognosis." (PMID 36686749, 2022). "Based on the literature, the expression level of IGF2BP1 in different types of cancer is changed." (PMID 35330456, 2022). "Interestingly, 14 of the 29 TCGA cancer types, including the three with the enriched senescence module, show ploidy-upregulation of IGFBPs and IGF2BPs, IGF2BP1 and IGF2BP3 being the most frequently encountered." (PMID 36499258, 2022). "Moreover, in 64 pairs of CRC and para-cancer tissues, IGF2BP1 mRNA was significantly higher in CRC compared with para-cancer tissues." (PMID 36114893, 2022).
cancer (continued). "FBXO45 is a therapeutic target in cancer and IGF2BP1 may also be considered a potential therapeutic target in PF_EPN_A." (PMID 36293188, 2022). "The mRNA binding protein IGF2BP1 is highly expressed in different types of solid human cancers." (PMID 35565249, 2022). "IGF2BP1 was upregulated in LUAD tissues compared with para-carcinoma tissues." (PMID 36249006, 2022). "Compared with para-carcinoma tissues, IGF2BP1 protein levels were upregulated in LUAD tissues." (PMID 36249006, 2022). "Notably, previous studies revealed that IGF2BP1, acted as a m6A reader, played an oncogenic role in cancer cells, through stabilizing methylated mRNAs of oncogenic proteins, including FSCN1, TK1, MARCKSL1, and MYC." (PMID 33853613, 2021). "It was also implied by our results that 24 m6A regulatory genes were related to the OS of patients with at least one cancer type, where some of the genes, including IGF2BP1/2/3, showed oncogenic features, and their increased expression was related to worse survival in patients with various cancers." (PMID 33816266, 2021). "IGF2BP1, a member of a conserved family of single-stranded RNA-binding proteins (IGF2BP1, 2, and 3), expresses in a broad range of fetal tissues and more than 16 cancers but only in a limited number of normal adult tissues." (PMID 34203267, 2021). "In view of the probably mutation-independent and sharp upregulation of IGF2BP1 in ATC, as well as its frequently reported expression in other aggressive cancers, our study strongly suggests expediting the clinical evaluation and also improvement of IGF2BP1-directed inhibitors in cancer therapy." (PMID 32719445, 2021). "A novel finding was the observation that the hallmark “unfolded protein response”, containing genes involved in maintaining the biosynthetic homeostasis of the endoplasmic reticulum (Schröder and Kaufman, 2005), is apparently regulated by IGF2BP1 in a conserved manner in cancer cells." (PMID 33829040, 2021). "IGF2BP1 could be utilized as a cancer biomarker for disease detection and therapeutic targets for personalized treatment." (PMID 34203267, 2021). "Moreover, IGF2BP1’s main and conserved role in cancer cells is the impairment of miRNA-directed mRNA degradation by recruiting target mRNAs to miRNA/RISC-devoid mRNPs." (PMID 34026620, 2021). "Thus, at present the main conserved target RNAs and pathways controlled by IGF2BP1 in cancer remain elusive." (PMID 33829040, 2021). "Aiming to focus on conserved, IGF2BP1-dependent pan-cancer expression patterns, we calculated Spearman correlation coefficients (ρ) between the RNA expression of IGF2BP1 and the consistently deregulated protein-coding genes in RNA-seq data of 31 solid tumor cohorts obtained from the TCGA project." (PMID 33829040, 2021). "SRF/IGF2BP1-dependent gene expression holds promise as a new cancer treatment strategy." (PMID 34794452, 2021). "Interact with RNA-binding proteins, including the m6A reader IGF2BP1, to induce cancer." (PMID 34888249, 2021). "Fourth, the findings showing IGF2BP1 overexpression promoted colony formation and chemoresistance were obtained in two CRC cell lines carrying a KRAS G13D mutation according to the Catalogue of Somatic Mutations In Cancer (COSMIC)." (PMID 34203267, 2021). "IGF2BP1 is a known essential regulator of intestinal development and cancer." (PMID 34779401, 2021). "In previous studies, we could show that IGF2BP1 stabilizes its RNA targets by antagonizing miRNA-impaired gene expression in different cancer models." (PMID 32545414, 2020). "This suggested that IGF2BP1 acts via largely cancer-specific pathways or that its most conserved effector pathway(s) across cancer types remained unknown." (PMID 32761127, 2020). "Activation of IGF2BP1 in cancer could result from reduced expression of let-7 microRNAs, which regulate thousands of transcripts, including the IGF2BPs." (PMID 32154328, 2020). "IGF2BP1-KO impaired spheroid growth, as previously observed in other cancer-derived cells." (PMID 32761127, 2020).